ENSG00000247130 (novel transcript)
Synonyms: LOC107986337
Gene: Long non-coding RNA gene on chromosome 4 (188,119,096 to 188,160,089, reverse strand). Ensembl gene ENSG00000247130.
Gene Ontology:
Molecular function: U4 snRNA binding
Biological process: formation of quadruple SL/U4/U5/U6 snRNP; spliceosomal tri-snRNP complex assembly
Cellular component: U4/U6 x U5 tri-snRNP complex; U6 snRNP